FAU (FAU ubiquitin like and ribosomal protein S30 fusion)
Description:
[Ubiquitin-like protein FUBI]: May have pro-apoptotic activity. [Small ribosomal subunit protein eS30]: Component of the 40S subunit of the ribosome. Contributes to the assembly and function of 40S ribosomal subunits.
Synonyms: RPS30; FLJ22986; Fub1; Fubi; MNSFbeta; asr1; S30; eS30; FAU1
Tractability: Small molecule: an approved drug acts on it; a structure with a bound ligand is known; a high-quality ligand is known. PROTAC: ubiquitination databases record sites on it; its protein half-life has been measured; a small molecule that binds it is known. Other modalities: a drug acting on it is in phase 2 or 3 trials.
Target class: Other cytosolic protein
Gene: Protein-coding gene on chromosome 11 (65,120,626 to 65,122,221, reverse strand). Ensembl gene ENSG00000149806.
Subcellular location: Cytoplasm (Small ribosomal subunit protein eS30); Nucleus
Subcellular location (Human Protein Atlas): Cytosol; Endoplasmic reticulum; Nucleoli
Pathways (Reactome):
Metabolism of proteins: Eukaryotic Translation Termination; Formation of a pool of free 40S subunits; Formation of the ternary complex, and subsequently, the 43S complex; GTP hydrolysis and joining of the 60S ribosomal subunit; L13a-mediated translational silencing of Ceruloplasmin expression; PELO:HBS1L and ABCE1 dissociate a ribosome on a non-stop mRNA; Peptide chain elongation; Ribosomal scanning and start codon recognition; SRP-dependent cotranslational protein targeting to membrane; Translation initiation complex formation; ZNF598 and the Ribosome-associated Quality Trigger (RQT) complex dissociate a ribosome stalled on a no-go mRNA
Disease: SARS-CoV-1 modulates host translation machinery; SARS-CoV-2 modulates host translation machinery; Viral mRNA Translation
Metabolism of RNA: Major pathway of rRNA processing in the nucleolus and cytosol; Nonsense Mediated Decay (NMD) enhanced by the Exon Junction Complex (EJC); Nonsense Mediated Decay (NMD) independent of the Exon Junction Complex (EJC)
Cellular responses to stimuli: Response of EIF2AK4 (GCN2) to amino acid deficiency
Developmental Biology: Regulation of expression of SLITs and ROBOs
Metabolism: Selenocysteine synthesis
Gene Ontology:
Molecular function: protein binding; RNA binding; structural constituent of ribosome; protein tag activity
Biological process: antibacterial humoral response; antimicrobial humoral immune response mediated by antimicrobial peptide; defense response to Gram-positive bacterium; innate immune response in mucosa; cytoplasmic translation; modification-dependent protein catabolic process; protein ubiquitination; translation
Cellular component: cytoplasm; cytosol; cytosolic ribosome; cytosolic small ribosomal subunit; endoplasmic reticulum; extracellular region; nucleolus; nucleus; small ribosomal subunit; nucleoplasm; ribosome
Genetic constraint (gnomAD): Loss-of-function variants: 0 observed, 15.27 expected, observed/expected ratio (o/e) 0, 90% interval 0 to 0.2. The upper end of that interval is the gene's LOEUF score, 0.2, which puts it in group 1 of 6, group 1 being the genes least tolerant of losing a copy. Missense variants: 125 observed, 183.98 expected, observed/expected ratio (o/e) 0.68, 90% interval 0.59 to 0.79. Synonymous variants: 70 observed, 74.4 expected, observed/expected ratio (o/e) 0.94, 90% interval 0.77 to 1.15.
Homologues: Orthologues: macaque FAU (98% identical), rat Fau (98% identical), chimpanzee FAU (98% identical), dog FAU (98% identical), guinea pig FAU (98% identical), mouse Fau (98% identical), pig FAU (95% identical), rabbit FAU (95% identical), rat LOC102548890 (91% identical), rat AABR07005572.2 (82% identical), tropical clawed frog fau (80% identical), zebrafish faua (78% identical), and 3 more.
Diseases named in the same sentence as FAU in open-access papers:
FAU is named in the same sentence as 20 diseases in open-access papers, as found by Europe PMC text mining. Sharing a sentence is not in itself a finding about the gene and the disease. The quoted sentences say what the papers report.
breast carcinoma (2 papers, 2022 to 2025). "The Ubiquitin‐like protein FUBI is encoded in humans by the FAU gene, whose down‐regulation in prostate, ovarian and breast cancer is significantly associated with poor prognosis." (PMID 40464359, 2025). "GDF11, CD151, PAFAH1B2 and YTHDF2 may play a pivotal role in the predisposition of metastasis to the bone from breast cancer, whilst DPP9, FAS, ZNF519, RPP14 and FAU may be actively involved in the adaptative colonisation of metastatic breast cancer cells in bone." (PMID 35685372, 2022).
colorectal cancer (1 paper, 2022). A primary or metastatic malignant neoplasm that affects the colon or rectum. "In addition, applying HEART on two subpopulations of megakaryocytes, we found several potential cancer biomarkers (CTTN, S100A4, S100A6, UBA52, FAU, and VIM, etc.)associated with colorectal cancer progression and metastasis in literature." (PMID 36523772, 2022).
dysplasia (1 paper, 2025). A usually neoplastic transformation of the cell, associated with altered architectural tissue patterns. "When we examined differential gene expression across these clonal populations, we identified a distinct transcriptional signature in the dysplasia origin clone, with several genes including TPM2, FAU, PCBD1, and APCDD1 showing consistent upregulation." (PMID 41360789, 2025).
ischemia (1 paper, 2025). A hypoperfusion of the BLOOD through an organ or tissue caused by a PATHOLOGIC CONSTRICTION or obstruction of its BLOOD VESSELS, or an absence of BLOOD CIRCULATION. "The expression of RPL10A, RPL14, RPL30, RPS18, FAU-40 (RPS30), and RPSA (Laminin Receptor, LR) was assessed in the myocardial and EAT tissues of MI, CABG and HL swine models and in LVSCs and EATDS challenged with ischemia." (PMID 39641799, 2025). "Importantly, the EATDS-derived exosomes have been unveiled for their potential cardiac responses and our previous findings identified major ribosomal proteins including RPL10A, RPL14, RPL30, RPS18, FAU-40 (RPS30), and RPSA (Laminin Receptor, LR) in the vesicles of ischemia-challenged EATDS." (PMID 39641799, 2025).
liver cancer (1 paper, 2021). An epithelial or non-epithelial malignant neoplasm that arises from the liver. "For lung cancer, GMPS, EPHA10, C10orf54, and MAGEA6 are highly expressed in different subtypes; for liver cancer, CMYA5, DEPDC6, FAU, VPS24, RCBTB2, LOC100133469, and SLC35B4 are significantly expressed in different subtypes." (PMID 33747053, 2021).
lung adenocarcinoma (1 paper, 2014). A carcinoma that arises from the lung and is characterized by the presence of malignant glandular epithelial cells. "Among them, only three genes (CTIF, FAU, and RPS28) are significantly down-regulated in tumors, implying NMD may not be inhibited in lung adenocarcinoma and thus cannot explain the large amount of intron retentions in tumors." (PMID 24646369, 2014).
melanoma (1 paper, 2020). A malignant, usually aggressive tumor composed of atypical, neoplastic melanocytes. "Our signature consists of diverse genes comprising protective (ATP1B1, CDAN1, FAU, and TNFSF14)) and risky (GPR87, KIT, SH3GL3, and PVRL1), which could be considered gene-related protective and risk patterns in melanoma." (PMID 32411243, 2020). "Finally, eight genes (GPR87, KIT, SH3GL3, PVRL1, ATP1B1, CDAN1, FAU, and TNFSF14) were identified to be closely associated with the OS in melanoma." (PMID 32411243, 2020). "In our study, we identified two gene expression patterns and generated an 8-gene-based (GPR87, KIT, SH3GL3, PVRL1, ATP1B1, CDAN1, FAU, and TNFSF14) gene signature that could recognize melanoma patients with a high risk of unfavorable clinical outcomes." (PMID 32411243, 2020). "We identified an 8-gene signature (i.e., GPR87, KIT, SH3GL3, PVRL1, ATP1B1, CDAN1, FAU, and TNFSF14) with independent prognostic value on melanoma." (PMID 32411243, 2020). "All eligible gene sets were analyzed, and the 8 genes (GPR87, KIT, SH3GL3, PVRL1, ATP1B1, CDAN1, FAU, and TNFSF14) with the greatest prognostic impact on melanoma." (PMID 32411243, 2020).
thymoma (1 paper, 2021). A neoplasm arising from the epithelial cells of the thymus. "The overall survival data from GEPIA2 demonstrated that low levels of FAU, RPS17, and RPS 24 were significantly associated with shorter survival, while high CCL4 was significantly associated with shorter survival in thymoma patients." (PMID 34760386, 2021).
cancer (4 papers, 2021 to 2023). A tumor composed of atypical neoplastic, often pleomorphic cells that invade other tissues. "Notably, RPL30 and FAU genes were consistently upregulated in all six different cancer types identified." (PMID 34760386, 2021).
tumor (2 papers, 2015 to 2022). "Fox is an antisense sequence to the cellular gene FAU, which indicates a putative tumor suppressor role for FAU." (PMID 26198235, 2015).
FAU also shares sentences with these, for which no sentence is quoted: infection (3 papers); Autoimmunity (1); chronic myeloid leukemia (1); hepatoma (1); infectious disease (1); lung carcinoma (1); macrosomia (1); ovarian carcinoma (1); Stroke (1); tauopathies (1).